CD4 (CD4 molecule)
Diseases named in the same sentence as CD4 in open-access papers (continued):
Sharing a sentence is not in itself a finding about the gene and the disease.
cholangiocarcinoma (28 papers, 2014 to 2025). A carcinoma that arises from the intrahepatic biliary tree (intrahepatic cholangiocarcinoma) or from the junction, or adjacent to the junction, of the right and left hepatic ducts (hilar cholangiocarcinoma). "The detection of CD4RA on TD CD4+ within mature T cells showed an inverse link with the risk of cholangiocarcinoma." (PMID 39050844, 2024). "In all three types of cholangiocarcinoma, Tregs, a dominant CD4+ T cell subtype, are strongly associated with poorer prognosis (DCC: p = 0.027; HC: p = 0.001; ICC: p = 0.017)." (PMID 35346322, 2022). "We found that a lower density of CD4+PD-1+ T cells is associated with a lower density of CD8+PD-1+ T cells consistently in all three types of cholangiocarcinoma." (PMID 35346322, 2022). "Additionally, a durable response was obtained in a patient with cholangiocarcinoma on infusion of autologous mutation-specific CD4+ cells which adopted a poly-functional Th1 phenotype." (PMID 25949894, 2015). "A study revealed an inverse relationship between the expression of NSDHL and the infiltration of NK cells, activated CD4+ T cells, and neutrophils in individuals who were diagnosed with cholangiocarcinoma." (PMID 39290276, 2024). "Tregs in cholangiocarcinoma often work with immunosuppressive cells to promote tumor progression and inhibit CD4+ T and CD8+ T lymphocytes activity in TME in a variety of ways." (PMID 39845973, 2024). "The immune profiling analysis of peripheral blood reveals an increased abundance of LAG-3hiPD-1hi memory CD4+ T cell subset in relapsed cholangiocarcinoma patients after gemcitabine plus cisplatin therapy, which provided a basis for the study of immune checkpoint inhibitors for CCA." (PMID 39845973, 2024). "Neoantigen-reactive CD4 T cells have also been shown to mediate clinical regression in a patient with cholangiocarcinoma when neoantigen-reactive CD4 T cells were adoptively transferred, further confirming the important contribution of neoantigen-specific CD4 T cells towards antitumor immunity." (PMID 36569934, 2022). "Serum cytokine profiles, lymphocyte subpopulations (B lymphocytes, CD8+ cytotoxic T lymphocytes, CD4+ T-helper lymphocytes, and NK cells), and cytotoxic activity of PBMCs against the cholangiocarcinoma cell line CL-6 were evaluated using cytometric bead array (CBA) with flow cytometry analysis." (PMID 33579265, 2021). "DC-activated T cells stimulated by antigenic peptides had higher populations of IFN-γ-positive CD4+ and CD8+ cells, which enhanced the killing ability of cholangiocarcinoma cells." (PMID 40070825, 2025). "Cholangiocarcinoma (CHOL) also showed high significance in its Tgammadelta (p = 0.6099), NK (p = 0.05944), and CD4+ (p = 0.6959) cell populations compared to BCC." (PMID 36612301, 2023). "On the other hand, in adaptive immune response of cholangiocarcinoma, tumor infiltrating lymphocytes (TIL) are a highly heterogeneous population, including CD8 + T cells, CD4 +T cells, B cells and Treg." (PMID 37064120, 2023). "The densities of mast cells, B cells, T helper 1 (Th1) CD4+ T cells, CD8+ T cells are significantly different between all three types of cholangiocarcinoma." (PMID 35346322, 2022). "The results showed that the levels of CD4+ and CD8+ T cells in cholangiocarcinoma with ATP2B1 protein overexpression were higher under different magnifications." (PMID 35875160, 2022). "The results showed that KLHL5 expression was not correlated with tumor purity (P = 8.28e−01), B cell (P = 7.92e−01), CD4+ T lymphocytes (P = 2.32e−01), CD8+ T lymphocytes (P = 6.33e−01), macrophages (P = 4.96e−01), or dendritic cell (P = 6.16e−01) level in cholangiocarcinoma." (PMID 33363208, 2020). "However, MKI67 expression was not related to the infiltration degrees of CD4+ T cells, CD8+ T cells, B cells, macrophages, DCs, or neutrophils within cholangiocarcinoma (CHOL)." (PMID 34724892, 2021).
adenoma (27 papers, 2012 to 2025). A neoplasm arising from the epithelium. "While some authors suggested that CD4+ cell concentration increases going through the adenoma–carcinoma sequence, others show that CD4+ T cells decrease as adenoma turns to CRC." (PMID 40149674, 2025). "In adenocarcinoma samples, the most abundant immune cells were resting memory CD4+ T cells (21%) followed by M0 macrophages (14%), regulatory T cells (8%) and activated memory CD4+ T cells (7%) compared to adenoma and CIS as observed previously." (PMID 40362431, 2025). "Th1 cells, identified by the CXCR3 or IFN-gamma expression in the tissue-derived CD4+ T cells, were upregulated from adenoma to carcinoma." (PMID 38343544, 2024). "Adenoma patients exhibited higher fractions of CD4 memory resting T cells compared to other groups., whereas carcinoma cases showed higher fractions of M0-type macrophages as opposed to other groups." (PMID 39408697, 2024). "Adenoma patients exhibited higher fractions of CD4 memory resting T cells compared to other groups (with a 0.95-fold decrease in CARD11+ compared to CARD11− adenoma)." (PMID 39408697, 2024). "Naïve CD4 T cells, activated/resting memory CD4 T cells, macrophage M0, activated mast cells, and neutrophils were highly infiltrating in adenoma." (PMID 36631756, 2023). "Only CD4 memory resting T cells were significantly lower in CRC organoids compared to adenoma organoids in both GSE57965 (p = 0.012) and GSE74843 cohorts (p = 0.046)." (PMID 33668713, 2021). "Both densely and sparsely granulated GH-adenomas had significantly more CD4+ cells than ACTH-adenomas, and significantly more CD8+ cells than null cell adenomas." (PMID 31649621, 2019). "Among the stromal cell populations we quantified, CD4+ T helper cells were the most abundant in small adenomas, and their densities increased significantly with size (1.9- and 1.5-fold in large lesions from the polypoid and nonpolypoid groups, respectively)." (PMID 27441558, 2016). "This is fully consistent with our data showing higher CD4+ T-cell densities in larger and more dysplastic adenomas." (PMID 27441558, 2016). "The adenoma detection rate in patients with CD4 lymphocyte counts less than 500 was 15% as compared to 47% in patients with CD4 counts greater than 500 (P = 0.03)." (PMID 27785180, 2012). "Surprisingly, even the immunocompetent patients with CD4 counts greater than 500 had a high adenoma detection rate (47%)." (PMID 27785180, 2012). "Surprisingly, patients with CD4 counts > 500 had significantly more adenomas than those with CD4 counts < 500, 47% vs 15% (P = 0.03)." (PMID 27785180, 2012). "Moreover, CD4+CD25+ Treg cells were decreased in HPs compared with grade III adenoma (1.96 vs. 19.6, P = 0.0097) or CRC (1.96 vs. 29.9, P = 0.0001)." (PMID 38343544, 2024). "However, compared with the control, a significantly increased percentage of circulating CD4+CD25+ Tregs was detected in the adenoma grade III (1.56 vs. 19.6, P = 0.0032) and CRC groups (1.56 vs. 29.9, P < 0.0001)." (PMID 38343544, 2024). "Moreover, the percentage of CD4+PD1+CXCR5+ cells decreased from adenoma grade I to III and even in CRC, primarily attributed to the change in programmed cell death protein 1 (PD1) but not CXCR5." (PMID 38343544, 2024). "We further analyzed the T follicular helper (Tfh) response, and CD4+PD1+CXCR5+ cells were significantly decreased in adenoma grade II (3.95 vs. 0.63, P = 0.0157), grade III (3.95 vs. 0.26, P = 0.0002), and CRC (3.95 vs. 0.16, P < 0.0001) compared with the control." (PMID 38343544, 2024). "Moreover, the upregulated Th2 cells, identified by the CCR4 expression in the tissue-derived CD4+T cells, from adenoma to CRC were consistent with the peripheral CD4+IL-4+ Th2 response." (PMID 38343544, 2024).
adenoma (continued). "By checking such biomarkers in the individual patients who donated the colorectal tissues from adjacent, adenoma, and carcinoma, the types or quantities of those CD4+ and CD8+ T-cell biomarkers in the stroma of adenoma and carcinoma were obviously larger than those in the adjacent." (PMID 35433435, 2022). "Furthermore, single-cell RNA-sequencing data showed that the expression of IL-2RA (CD25) and FOXP3, the key markers of Treg cells, was increased from adenoma to carcinoma in the tissue-derived CD4+ T cells, which is consistent with the changes in peripheral Treg cells." (PMID 38343544, 2024). "Regarding IL-10 levels in premalignant and malignant CR lesions, double immunohistochemistry revealed more abundant CD4/CD25 and IL-10/FoxP3 dual-positive Tregs within the tumor stroma in both adenomas and carcinomas." (PMID 40149674, 2025). "The highest fractions of immune cells in adenoma samples compared to CIS and adenocarcinoma were macrophages (23%) followed by naïve CD4+ T cells (18%), and memory B cells (17%), consistent with previous findings." (PMID 40362431, 2025). "The CD4+CCR6+ Th17 cell proportion decreased in CRC when compared with the healthy control group (23.1 vs. 11.2, P = 0.0279) or adenoma grade I (24.3 vs. 11.2, P = 0.0163) or even adenoma grade II (21.7 vs. 11.2, P = 0.0042)." (PMID 38343544, 2024). "CD4+IL-4+ Th2 cells were increased in the CRC group when compared with those in HPs and adenoma grade I (2.11 vs. 5.63, P = 0.0027; 2.20 vs. 5.63, P = 0.0049)." (PMID 38343544, 2024). "The deduction was also endorsed by the enriched biomarkers of CD4+ and CD8+ T cells in the stroma of adenoma and carcinoma." (PMID 35433435, 2022). "The IHC images provided supportive evidence for the proteomic deduction of higher CD4+ and CD8+ T-cell infiltration in the microenvironment of adenoma and carcinoma." (PMID 35433435, 2022). "The infiltration of CD4+ and CD8+ T cells was relatively scant in these adenomas, but pituitary growth hormone (GH) adenomas exhibited significantly more CD4+ and CD8+ T cells than non-GH adenomas." (PMID 33362722, 2020). "In general, these cells were much less abundant than CD4+ T helper cells in adenomas, with CD8+/CD4+ ratios of 0.4 (small polypoid lesions), 0.3 (large polypoid lesions), and 0.23 (nonpolypoid lesions of all sizes)." (PMID 27441558, 2016). "In the stroma of our adenomas, macrophages (CD68+) were slightly more numerous than CD8+ or FOXP3+ T cells, but they were far less abundant than CD4+ T cells." (PMID 27441558, 2016). "Further, they reported that while overall T lymphocyte infiltration in pituitary adenomas was sparse, growth-hormone-secreting adenomas had higher levels of CD4+ and CD8+ T cell infiltration than non-growth-hormone-secreting adenomas." (PMID 36768342, 2023). "Moreover, significantly higher IL-17A, CD4, and class II MHC transactivator mRNA levels were found in the pituitary glands of patients diagnosed with primary hypophysitis compared with adenoma and normal gland." (PMID 35205804, 2022). "Furthermore, CD3+, CD4+, and CD45+ cells trended to a higher expression in atypical adenomas compared to typical adenomas." (PMID 27655724, 2016). "When analyzed by subclass of tumor, both CD3+ and CD4+ populations were significantly increased in functioning adenomas compared to non-functioning adenomas (p = 0.019 and p = 0.0001, respectively)." (PMID 27655724, 2016). "Macrophages interacted with nearly all immune cell types specifically exhausted CD8+ T cells (CD8+ Tex) CD8+ Teff, CD4+ Treg 1 and Th17 by SPP1–CD44 interaction, which only occurred in tumour sites, and no expression of SPP1 in macrophages from normal bowel tissue and adenoma was observed." (PMID 39934971, 2025). "Other ILC subsets, such as CD4(+) ILC1, CD5(+) mature ILC1, immature ILCs, and LT-ILC155, may also play important roles in FAP-related tumorigenesis and should be explored in future studies to further clarify the immune landscape of FAP adenomas." (PMID 40280932, 2025).
adenoma (continued). "Indeed, the infiltration patterns of CD4+, CD8+ TILs, DCs and other immune cells were shown to be progressively altered in the normal-adenoma-carcinoma sequence, and also in the low grades of adenomas." (PMID 31072360, 2019). "Interestingly, the only adenoma (#5) was strongly infiltrated with CD3+CD4+ T cell, but cytotoxic T cells were virtually absent - partially matching with observations from human Lynch-associated tumors." (PMID 27447752, 2016). "Immunofluorescence experiments also support these results as conventional CD4+ T cells within adenomas are usually luminally clustered instead of distributed throughout the lamina propria, while CD8+ T cells are virtually absent from adenoma tissue." (PMID 33628741, 2021). "Similarly, also adenomas displayed a specific enrichment in F4/80+ cells, but not in either MPO- or CD4-positive cells, thus possibly indicating that BRAFV600E-driven adenomas may preferentially recruit macrophages rather than neutrophils or lymphocytes." (PMID 35145078, 2022).
bladder tumors (27 papers, 2016 to 2025). "This increase in the proportion of CD4+ TEM cells is relevant, since CD4+ T-cells have been described as potent cytotoxic cells and very recently, in bladder tumors, have been linked to the efficacy of immunotherapy." (PMID 36304456, 2022). "Response to treatment was significantly associated with elevated urinary T cells including CD8+ and IFNγ+ CD4+ T cells, suggesting potential reinforcement of immune responses by neoadjuvant αPD-1 and αCTLA-4 against bladder tumor cells." (PMID 38784962, 2024). "Cytotoxic CD4+ T cells recognised MHC-II antigens to kill the bladder tumor cells and lyse autologous tumor cells in a way that is inhibited by autologous Treg." (PMID 36338973, 2022). "Specifically, a recent work highlighted the enrichment of CD4 T cells in human bladder tumors, with a high presence of cytotoxic CD4 T cell signatures." (PMID 34064410, 2021). "Our results as well suggest a systemic suppression of immune response by CD4+CD25+ Tregs in the bladder tumor tissue." (PMID 32484812, 2020). "Altogether, we suggest that the liposome-derived internalization of BCG-CWS into bladder tumor tissues increases IL-6 production and CD4 infiltration, thereby increasing the antitumor efficacy." (PMID 31817179, 2019). "Co-incubation of CD45+ cells isolated from MB49luc bladder tumors of control Ig–treated mice with either CD4+ or CD8+ T cells from naïve mice (ratios of 1:2 and 1:4) significantly reduced the percentage of CD4+ or CD8+ T cells expressing Ki67." (PMID 31186063, 2019). "NHS-muIL12 administration resulted in temporal-dependent reductions in the number of MDSCs, macrophages and tumor-associated TGF-β, which culminated in a re-ignition of CD4+ and CD8+ T cells to elicit potent antitumor responses against MB49luc bladder tumors." (PMID 31186063, 2019). "tumor were CD8+ T and NK cells, whereas to effectively reduce MB49 bladder tumors required both CD4+ and CD8+ T cells." (PMID 31186063, 2019). "Furthermore, an independent study noted that CD4+ T cells isolated from bladder tumors exhibited substantial cytotoxicity when cultured in vitro, inducing apoptosis in tumor cells." (PMID 38292868, 2024). "In addition, it was found that cytotoxic CD4+ subsets in bladder tumors were clonally expanded, potentially resulting from recognition of bladder tumor antigens." (PMID 37727793, 2023). "In addition, previous work from our own group demonstrated the dependence on a Coxsackievirus A21-induced CD4 response to control the outgrowth of MB49 bladder tumors in mice." (PMID 33665363, 2021). "Consistent with an active cell-mediated immunosuppressive TME, co-culturing CD45+ cells from MB49luc bladder tumors from control Ig–treated mice with splenic effector cells reduced the percentage of Ki67-expressing splenic CD4+ and CD8+ cells in response to αCD3/28 to 21.3 and 40.2%, respectively." (PMID 31186063, 2019). "It is intriguing to point out that in the control Ig–treated mice, in which MB49luc bladder tumor burdens increased during the 72–144-h time interval, CD4+ and CD8+ effector T cell numbers actually increased, yet their activation status fell, providing additional evidence for immunosuppression." (PMID 31186063, 2019). "Bladder tumors possess both known and novel CD4+ T cell populations, including multiple populations of regulatory (CD4reg) and central memory (CD4cm) cells, as well as novel populations of cytotoxic (CD4cyto) CD4+ T cells expressing cytolytic effectors and granule-associated proteins." (PMID 30400822, 2018). "This mechanistic convergence aligns with recent reports: ARID1A-mutant bladder tumors exhibit higher TMB and improved ICIs outcomes, and a significant increase in CD4+ T-lymphocyte infiltration has been observed in ICIs responders." (PMID 41438758, 2025). "Four days later, bladder tumors were harvested and stained for overall immune cells (CD45+), MDSCs, CD8+ T cells and CD4+ T cells." (PMID 37901214, 2023).
bladder tumors (continued). "Suppression of CD4+ and CD8+ T cells in response to αCD3/28 stimulation was dependent on the number of CD45+ cells isolated from MB49luc bladder tumors and added to the suppression assay." (PMID 31186063, 2019). "During the immune cell type analysis, we observed that CD4+ T cells and type‐2 DCs decreased, while CD8+ T cells and plasmacytes significantly increased in all three batches of recurrent bladder tumours, indicating an expected stronger immune response in recurrent tumours." (PMID 37488671, 2023). "Indeed, iDAMP blockade resulted in a significantly increased CD3+ T-cell infiltration as well as CD4+ and CD8+ T-cell subsets when compared with the GC-treated bladder tumors." (PMID 35347124, 2022). "Furthermore, previous findings established that CD4+ and CD8+ T cells were both required for the antitumor effects of NHS-muIL12 treatment of mice bearing MB49luc bladder tumors." (PMID 31186063, 2019). "Successful antitumor efficacy directed at the MB49luc bladder tumors was lost when either CD4+ or CD8+ T cells were absent, indicating the requirement of an intact host immune system." (PMID 31186063, 2019). "With NHS-muIL12 treatment, the reductions of MB49luc bladder tumor growth was not accompanied by any discernable increase in the number of CD4+ and CD8+ effector T cells, yet their activation status was increased." (PMID 31186063, 2019). "We performed droplet single-cell RNA and paired T cell receptor (TCR) sequencing of CD4+ and CD8+ T cells isolated from localized bladder tumors and paired adjacent non-malignant tissue including patients who received anti-PD-L1 antibody prior to surgery." (PMID 30400822, 2018). "Notably, cytotoxic CD4+ T cells, rather than typical CD8+ T cells, were significantly enriched in bladder tumors." (PMID 36338973, 2022). "As a positive control, in the absence of bladder tumor isolated CD45+ cells, the percentage of splenic CD4+ and CD8+ T cells from naïve mice that expressed Ki67 following αCD3/28 in vitro stimulation was 66.6 and 81.6%, respectively (right panels: labeled T cells only)." (PMID 31186063, 2019).